IGLV2-8 (immunoglobulin lambda variable 2-8)
Description:
V region of the variable domain of immunoglobulin light chains that participates in the antigen recognition. Immunoglobulins, also known as antibodies, are membrane-bound or secreted glycoproteins produced by B lymphocytes. In the recognition phase of humoral immunity, the membrane-bound immunoglobulins serve as receptors which, upon binding of a specific antigen, trigger the clonal expansion and differentiation of B lymphocytes into immunoglobulins-secreting plasma cells. Secreted immunoglobulins mediate the effector phase of humoral immunity, which results in the elimination of bound antigens. The antigen binding site is formed by the variable domain of one heavy chain, together with that of its associated light chain. Thus, each immunoglobulin has two antigen binding sites with remarkable affinity for a particular antigen. The variable domains are assembled by a process called V-(D)-J rearrangement and can then be subjected to somatic hypermutations which, after exposure to antigen and selection, allow affinity maturation for a particular antigen.
Synonyms: IGLV28; V1-2
Tractability: Small molecule: it has a high-quality binding pocket. Antibody: its Gene Ontology location is reachable by antibodies, with high confidence; UniProt places it where antibodies can reach, with medium confidence; UniProt predicts a signal peptide or a membrane-spanning region.
Gene: Immunoglobulin variable (V) gene on chromosome 22 (22,822,658 to 22,823,289, forward strand). Ensembl gene ENSG00000278196.
Subcellular location: Secreted; Cell membrane
Pathways (Reactome):
Immune System: Antigen activates B Cell Receptor (BCR) leading to generation of second messengers; CD22 mediated BCR regulation; Classical antibody-mediated complement activation; FCERI mediated Ca+2 mobilization; FCERI mediated MAPK activation; FCERI mediated NF-kB activation; FCGR activation; Fc epsilon receptor (FCERI) signaling; Immunoregulatory interactions between a Lymphoid and a non-Lymphoid cell; Initial triggering of complement; Regulation of Complement cascade; Regulation of actin dynamics for phagocytic cup formation; Role of LAT2/NTAL/LAB on calcium mobilization; Role of phospholipids in phagocytosis
Disease: FCGR3A-mediated IL10 synthesis; FCGR3A-mediated phagocytosis; Potential therapeutics for SARS
Hemostasis: Cell surface interactions at the vascular wall
Vesicle-mediated transport: Scavenging of heme from plasma
Gene Ontology:
Molecular function: antigen binding
Biological process: immune response
Cellular component: extracellular region; immunoglobulin complex; plasma membrane
Homologues: Orthologues: chimpanzee IGLV2-8 (82% identical). Paralogues in human: IGLV2-11 (93% identical), IGLV2-14 (90% identical), IGLV2-18 (90% identical), IGLV2-23 (86% identical), IGLV1-40 (73% identical), IGLV2-33 (71% identical), IGLV1-50 (69% identical), IGLV1-44 (67% identical), IGLV1-47 (66% identical), IGLV1-51 (64% identical), IGLV6-57 (64% identical), IGLV1-36 (63% identical), and 81 more.
Diseases named in the same sentence as IGLV2-8 in open-access papers:
IGLV2-8 is named in the same sentence as 3 diseases in open-access papers, as found by Europe PMC text mining. Sharing a sentence is not in itself a finding about the gene and the disease.
glioblastoma (1 paper, 2023). The most malignant astrocytic tumor (WHO grade IV).
IGLV2-8 also shares sentences with these, for which no sentence is quoted: carcinoma (1 paper); hypertrophy (1).